PCDHGB7 (protocadherin gamma subfamily B, 7)
Description:
Potential calcium-dependent cell-adhesion protein. May be involved in the establishment and maintenance of specific neuronal connections in the brain.
Synonyms: PCDH-gamma-B7; ME6
Tractability: Antibody: UniProt places it where antibodies can reach, with medium confidence; UniProt predicts a signal peptide or a membrane-spanning region; its Gene Ontology location is reachable by antibodies, with medium confidence. PROTAC: ubiquitination databases record sites on it; its protein half-life has been measured.
Gene: Protein-coding gene on chromosome 5 (141,417,645 to 141,512,975, forward strand). Ensembl gene ENSG00000254122.
Subcellular location: Cell membrane
Subcellular location (Human Protein Atlas): Plasma membrane; Vesicles; Cytosol; Nucleoplasm
Gene Ontology:
Molecular function: cell adhesion molecule binding; calcium ion binding
Biological process: cell adhesion; homophilic cell-cell adhesion
Cellular component: plasma membrane; membrane
Genetic constraint (gnomAD): Loss-of-function variants: 34 observed, 63.63 expected, observed/expected ratio (o/e) 0.53, 90% interval 0.41 to 0.71. The upper end of that interval is the gene's LOEUF score, 0.71, which puts it in group 2 of 6, group 1 being the genes least tolerant of losing a copy. Missense variants: 1,151 observed, 1,255.8 expected, observed/expected ratio (o/e) 0.92, 90% interval 0.87 to 0.96. Synonymous variants: 458 observed, 531.33 expected, observed/expected ratio (o/e) 0.86, 90% interval 0.8 to 0.93.
Homologues: Orthologues: mouse Pcdhgb7 (82% identical). Paralogues in human: PCDHGB6 (78% identical), PCDHGB5 (72% identical), PCDHGB2 (70% identical), PCDHGB1 (70% identical), PCDHGB4 (69% identical), PCDHGB3 (67% identical), PCDHGA12 (52% identical), PCDHGA11 (52% identical), PCDHGA5 (51% identical), PCDHGA6 (51% identical), PCDHGA10 (50% identical), PCDHGA9 (50% identical), and 49 more.
Diseases named in the same sentence as PCDHGB7 in open-access papers:
PCDHGB7 is named in the same sentence as 22 diseases in open-access papers, as found by Europe PMC text mining. Sharing a sentence is not in itself a finding about the gene and the disease. The quoted sentences say what the papers report.
breast carcinoma (8 papers, 2016 to 2025). "Meanwhile, the detection of PCDHGB7 mRNA expression in breast tissue and breast cancer cell lines e indicated that PCDHGB7 expression was downregulated in breast cancer tissue due to hypermethylation of the promoter region." (PMID 39949775, 2025). "Conversely, both cell lines attained additional chemoresistance to carboplatin when the PCDHGB7 gene was knocked down (P < 0.001), confirming that PCDHGB7 positively enhances the chemosensitivity of breast cancer cells to carboplatin." (PMID 31379979, 2019). "Similar results were also obtained in breast cancer cell lines by our group, suggesting that PCDHGB7 gene expression is significantly reduced in breast cancer due to hypermethylation of the promoter region." (PMID 31379979, 2019). "In this study, by constructing PCDHGB7 knockdown and overexpression models and HSPA9 knockdown breast carcinoma cell models, we confirmed the positive correlation between the PCDHGB7 level and the cell's chemosensitivity to carboplatin." (PMID 31379979, 2019). "Our group also detected PCDHGB7 mRNA expression in 40 paired breast cancer tissues and matched normal breast tissues and found PCDHGB7 expression was reduced in breast cancer tissue." (PMID 31379979, 2019). "We demonstrated that PCDHGB7 also acts as a tumor suppressor in breast cancer by enhancing the proliferation and invasion of breast carcinoma cell lines." (PMID 31379979, 2019). "PCDHGB7, P16, and RASSF1a (although the methylation frequency of RASSF1a was lower in the serum in this study, it was generally high in breast cancer tissues) were selected." (PMID 31198475, 2019). "In our previous study, we found a remarkable abnormal methylation modification of the PCDHGB7 gene in breast cancer." (PMID 31379979, 2019). "Among these genes, abnormal methylation of the PCDHGB7 gene was seen in approximately 80% of breast cancer." (PMID 31379979, 2019). "PCDHGB7 mRNA levels in two breast cancer cell lines were verified in overexpressed and control cells." (PMID 31379979, 2019). "The genes we selected, SFN, P16, hMLH1, PCDHGB7 and RASSF1a had the most frequency of methylation in breast cancer samples in our previous research and the methylation of some of the genes happened at the early stage of breast cancer." (PMID 26918343, 2016). "In summary, the six-marker panel with HOXD13, SFN, RASSF1a, P16, PCDHGB7, and hMLH1 exhibits significantly aberrant methylation in serum cfDNA from breast cancer patients compared with both age-matched healthy women and women with a benign breast disease." (PMID 26918343, 2016). "Few reports have been made to claim PCDHGB7 could be a novel marker for breast cancer, non-Hodgkin’s lymphoma, and hepatocellular carcinoma." (PMID 39949775, 2025). "Besides, PCDHGB7 hypermethylation gene was detected in approximately 80% of breast cancer, and PCDHGB7 expression was reduced in breast cancer tissue." (PMID 35059435, 2021). "Accumulating data on these methylation markers including the six genes tested in this study (HOXD13, SFN, RASSF1a, P16, PCDHGB7, and hMLH1) is of interest for further evaluation as serum- or serum-based biomarkers for the detection and monitoring of breast cancer patients." (PMID 26918343, 2016). "However, the roles of PCDHGB7 in the progression and treatment of breast cancer are unclear." (PMID 31379979, 2019). "The TCGA data showed that young-age breast cancer patients have a lower level of expression of RANBP3L, GLYATL-1, and ESR1, whereas ACVR2A, SERPINE2, and PCDHGB7 have higher expression in young-age breast cancer patients compared to old age patients." (PMID 36672708, 2023).
breast carcinoma (continued). "In our study, we also detected the HSPA9 mRNA levels in breast cancer cells (Hs578T and BT549) with PCDHGB7 knockdown and overexpression." (PMID 31379979, 2019). "Our results demonstrated that PCDHGB7 inhibits HSPA9 and increases chemosensitivity to carboplatin via inducing apoptosis in breast cancer." (PMID 31379979, 2019). "Conversely PCDHGB7 and SFN exhibited better sensitivities in breast cancer (55.60% and 73.51%), but the specificity was unsatisfied." (PMID 26918343, 2016). "By analysing the TCGA dataset, we further revealed a negative correlation between PCDHGB7 mRNA level and the mRNA levels of more than half of the genes (25 out of 49) that regulate ribosome biogenesis in breast cancer." (PMID 40898765, 2025). "PCDHGB7 and HSPA9 represent potential therapeutic targets for chemosensitivity in breast cancer." (PMID 31379979, 2019). "PCDHGB7 and HSPA9 potentially represent novel targets of chemotherapy in breast cancer." (PMID 31379979, 2019). "In this study, we assessed the promoter methylation of an six-gene panel (SFN, P16, hMLH1, HOXD13, PCDHGB7 and RASSF1a) in serum samples by using MethyLight, to investigate whether it could be used for diagnosis of breast cancer or not." (PMID 26918343, 2016).
cervical cancer (3 papers, 2023 to 2025). A primary or metastatic malignant neoplasm involving the cervix. "The level of PCDHGB7 methylation has been then proven to be an early and reliable diagnosis indicator of cervical cancer and has shown good diagnostic efficacy in the diagnosis of malignant body fluids." (PMID 39949775, 2025). "Recently, PCDHGB7 methylation was identified as a diagnosis indicator for cervical cancer, endometrial cancer, and malignant body fluids which attracted more oncologists’ attention since its huge translational potential." (PMID 39949775, 2025). "It has been reported that the level of PCDHGB7 methylation level in malignant body fluids serves as a promising biomarker for cancer, particularly the cervical cancer." (PMID 39949775, 2025). "Our previous research identified hypermethylated PCDHGB7 as a novel cancer marker with discernible value for early cervical cancer detection and modified methylation-sensitive restriction enzyme qPCR (MSRE-qPCR) to quantify its methylation status." (PMID 38317152, 2024).
non-Hodgkin lymphoma (3 papers, 2019 to 2025). Distinct from Hodgkin lymphoma both morphologically and biologically, non-Hodgkin lymphoma (NHL) is characterized by the absence of Reed-Sternberg cells, can occur at any age, and usually presents as a localized or generalized lymphadenopathy associated with fever and weight loss. "In one study, PCDHGB7 was reported to be significantly methylated in non-Hodgkin's lymphoma, whereas PCDHGB7 expression in other tumors and its role and mechanism in tumorigenesis and progression have not been reported." (PMID 31379979, 2019). "As a member of the protocadherin family, the biology of PCDHGB7 has been widely documented in the central nervous system and in diseases such as non-Hodgkin's lymphoma." (PMID 31379979, 2019). "PCDHGB7 is reported to be significantly hypermethylated in non-Hodgkin’s lymphoma." (PMID 35059435, 2021).
endometrial cancer (2 papers, 2021 to 2025). Primary or metastatic malignant neoplasm involving the endometrium (mucous membrane that lines the endometrial cavity). "To evaluate the bioinformatics analysis results, we validated the methylation level of PCDHGB7 in 33 endometrial cancer samples from EC patients, and 105 BE or tumor-adjacent endometrial tissue samples using MSRE-qPCR." (PMID 35059435, 2021).
lung carcinoma (2 papers, 2024 to 2025). "In lung cancer tissues, high expression of PCDHGB7 is associated with multiple pathways, such as homologous recombination, DNA mismatch repair, and JAK-stat pathway, while significantly increasing the infiltration of immune system negatively regulated cells." (PMID 39949775, 2025). "Analysis of mutation landscape and immune infiltration suggested that PCDHGB7 expression is related to the efficacy of lung cancer immunotherapy." (PMID 39949775, 2025). "As gene mutations play an important role in lung cancer development, we next characterized the genomic mutation profile correlated with PCDHGB7 expression in lung cancer." (PMID 39949775, 2025). "Similar to other investigations, we also found high expression of PCDHGB7 in lung cancer, we further deciphered the role of PCDHGB7 in lung cancer that has not yet been fully explored yet." (PMID 39949775, 2025). "Plasma PCDHGB7 methylation and protein levels can be used as novel biomarkers for predicting the efficacy of immunotherapy in lung cancer." (PMID 39949775, 2025). "The PCDHGB7 methylation and expression in plasma was also detected in lung cancer patients collected in our clinical center in order to reveal the association between PCDHGB7 and immunotherapy response." (PMID 39949775, 2025). "Nevertheless, further immunohistochemical and lung cancer cell line detection data are required to ascertain the connection between PCDHGB7 promoter methylation and expression." (PMID 39949775, 2025). "In this study, we investigated the role of PCDHGB7 in lung cancers via integration of multiple bioinformatics methods." (PMID 39949775, 2025). "Plasma PCDHGB7 methylation and protein levels can be used as novel biomarkers for predicting the efficacy of immunotherapy against lung cancer." (PMID 39949775, 2025). "Given the high expression of PCDHGB7 within pulmonary tissue, we aimed to elucidate the role of PCDHGB7 in lung cancer." (PMID 39949775, 2025). "In summary, our research aim to contribute to a better understanding of the role of PCDHGB7 in lung cancer, and expose the potential of PCDHGB7 to be a novel biomarker for lung cancer." (PMID 39949775, 2025). "PCDHGB7 has been found to upregulated in lung cancer, while the specific function of PCDHGB7 remains to be further clarified." (PMID 39949775, 2025). "The dynamic changes in methylation and expression levels of plasma PCDHGB7 can serve as biomarkers for immunotherapy of lung cancer." (PMID 39949775, 2025). "Two lung cancer immunotherapy cohorts from our clinical center were enrolled to detect the relationship between methylation and protein levels of PCDHGB7 in plasma and immunotherapy outcomes." (PMID 39949775, 2025). "Altogether, these results suggest that cfDNA hypermethylation of TAGMe and PCDHGB7 are cancer-specific features in MPE samples from lung cancer patients and hold potential as universal markers for malignancy in body fluids." (PMID 38587071, 2024). "The involvement of PCDHGB7 in these critical biological processes suggests that it could be a pivotal factor in both the development and progression of lung cancer." (PMID 39949775, 2025). "These comprehensive investigations suggest that PCDHGB7 might play a significant role in lung cancer DNA mismatch repair." (PMID 39949775, 2025). "Additionally, PCDHGB7 plays a significant role in DNA homologous recombination and mismatch repair within lung cancer." (PMID 39949775, 2025). "Next, we used R script to examine the prognostic relevance of PCDHGB7 expression in lung cancer." (PMID 39949775, 2025). "In addition to the clinical limitations, there is a pressing need for further cellular and animal studies to explore the biological functions of PCDHGB7 in lung cancer." (PMID 39949775, 2025). "Furthermore, our ensemble pathway enrichment analysis indicated that PCDHGB7 may affect the efficacy of lung cancer immunotherapy by regulating the interaction between cytokines and their paired receptors." (PMID 39949775, 2025).
lung carcinoma (continued). "Therefore, high expression of PCDHGB7 may lead to disorders in DNA damage repair and anti-tumor immune regulation, resulting in poor responsiveness of lung cancer patients to immunotherapy." (PMID 39949775, 2025). "However, it remains uncertain whether the PCDHGB7 methylation level in peripheral blood from patients with lung cancer could serve as a novel biomarker of immunotherapy efficacy." (PMID 39949775, 2025). "Additionally, we found that decreased PCDHGB7 expression may be linked to increased methylation in LUAD and LUSC when we used MEXPRESS to investigate the relationship between PCDHGB7 expression and CpG islands in lung cancer." (PMID 39949775, 2025). "To investigate the function of PCDHGB7 in lung cancer with greater precision, we conducted GO and KEGG pathway enrichment analyses based on the differentially expressed genes between the PCDHGB7-high and PCDHGB7-low groups." (PMID 39949775, 2025). "Utilizing the OncoDB and MEXPRESS databases, we examined the methylation status of the PCDHGB7 gene in lung cancer and discovered a negative correlation between the methylation level and PCDHGB7 expression at most gene sites, particularly the promoter region (2 KB upstream of the gene)." (PMID 39949775, 2025).
bladder cancer (1 paper, 2025). "Results showed that PCDHGB7 evaluation outperformed urine cytology in bladder cancer (82.1% vs. 34.5%), ureter cancer (78.1% vs. 34.4%), and renal pelvis cancer (90.9% vs. 22.7%), indicating this methylation‐dependent detection had higher efficiency." (PMID 40708980, 2025).
breast tumors (1 paper, 2025). "According to earlier research using public database analysis, over 80% of breast tumors display aberrant methylation of the PCDHGB7 gene." (PMID 39949775, 2025).
lung adenocarcinoma (1 paper, 2025). A carcinoma that arises from the lung and is characterized by the presence of malignant glandular epithelial cells. "PCDHGB7 expression was downregulated in lung adenocarcinoma (LUAD) and lung squamous cell carcinoma (LUSC) and associated with tumor prognosis." (PMID 39949775, 2025).
non-small cell lung carcinoma (1 paper, 2025). A group of at least three distinct histological types of lung cancer, including non-small cell squamous cell carcinoma, adenocarcinoma, and large cell carcinoma. "PCDHGB7 expression and methylation are prognostic and immunological biomarkers in non-small cell lung cancer." (PMID 39949775, 2025). "Our data illustrated that PCDHGB7 expression and methylation are prognostic and immunological biomarkers in non-small cell lung cancer." (PMID 39949775, 2025). "We further analyzed plasma PCDHGB7 levels in a prospective clinical cohort of elderly patients with non-small cell lung cancer." (PMID 39949775, 2025).
triple-negative breast carcinoma (1 paper, 2019). An invasive breast carcinoma which is negative for expression of estrogen receptor (ER), progesterone receptor (PR), and human epidermal growth factor receptor 2 (HER2). "Our findings present PCDHGB7 and HSPA9 as potential therapeutic targets for further studies in attempts to overcome chemoresistance in triple-negative breast cancer." (PMID 31379979, 2019).